ESYT3 (extended synaptotagmin 3)
Description:
Binds glycerophospholipids in a barrel-like domain and may play a role in cellular lipid transport (By similarity). Tethers the endoplasmic reticulum to the cell membrane and promotes the formation of appositions between the endoplasmic reticulum and the cell membrane.
Synonyms: E-Syt3; FAM62C; CHR3SYT
Tractability: Antibody: UniProt places it where antibodies can reach, with high confidence; its Gene Ontology location is reachable by antibodies, with high confidence; UniProt predicts a signal peptide or a membrane-spanning region.
Gene: Protein-coding gene on chromosome 3 (138,434,586 to 138,481,686, forward strand). Ensembl gene ENSG00000158220.
Subcellular location: Cell membrane; Endoplasmic reticulum membrane
Pathways (Reactome):
Transport of small molecules: Glycosphingolipid transport
Gene Ontology:
Molecular function: protein binding; calcium ion binding; calcium-dependent phospholipid binding; phosphatidylcholine binding; phosphatidylethanolamine binding; phosphatidylinositol binding; lipid binding
Biological process: lipid transport
Cellular component: cytoplasmic side of plasma membrane; endoplasmic reticulum membrane; endoplasmic reticulum-plasma membrane contact site; organelle membrane contact site; plasma membrane
Genetic constraint (gnomAD): Loss-of-function variants: 96 observed, 104.08 expected, observed/expected ratio (o/e) 0.92, 90% interval 0.78 to 1.09. The upper end of that interval is the gene's LOEUF score, 1.09, which puts it in group 4 of 6, group 1 being the genes least tolerant of losing a copy. Missense variants: 1,057 observed, 1,073.5 expected, observed/expected ratio (o/e) 0.98, 90% interval 0.94 to 1.04. Synonymous variants: 404 observed, 438.32 expected, observed/expected ratio (o/e) 0.92, 90% interval 0.85 to 1.
Homologues: Orthologues: chimpanzee ESYT3 (99% identical), macaque ESYT3 (97% identical), pig ESYT3 (89% identical), dog ESYT3 (87% identical), guinea pig ESYT3 (87% identical), rabbit ESYT3 (84% identical), mouse Esyt3 (84% identical), rat Esyt3 (84% identical), zebrafish esyt3 (38% identical), Drosophila melanogaster Esyt2 (27% identical). Paralogues in human: ESYT2 (40% identical), ESYT1 (37% identical).
Diseases named in the same sentence as ESYT3 in open-access papers:
ESYT3 is named in the same sentence as 6 diseases in open-access papers, as found by Europe PMC text mining. Sharing a sentence is not in itself a finding about the gene and the disease. The quoted sentences say what the papers report.
Achalasia (2 papers, 2024). A disorder of esophageal motility characterized by the inability of the lower esophageal sphincter to relax during swallowing and by inadequate or lacking peristalsis in the lower half of the body of the esophagus. "Whole-exome sequencing (WES) on achalasia patients and controls revealed an association between the disease and common missense variants rs1705003 (CUTA) and rs1126511 (HLA-DPB1), and three rare variants (CREB5, ESYT3, and LPIN1) in an independent cohort." (PMID 38792545, 2024).
adenoma (1 paper, 2022). A neoplasm arising from the epithelium. "Six predicted Mir34a targets (Arhgap44, Ccnjl, Clec16a, Esyt3, Golga7b, Grap) were up-regulated in both Mir34a-deficient adenomas and tumoroids." (PMID 36147476, 2022).
tumor (2 papers, 2016 to 2024). "Altogether, this work innovatively proposed a radiotherapy response classification for LUAD, and discovered ESYT3 acted as a tumor suppressor and a novel radioimmune response sensitizer." (PMID 39103908, 2024). "In this study, we innovatively proposed a radiotherapy response classification for LUAD, and discovered ESYT3 served as a tumor suppressor and radioimmune response sensitizer." (PMID 39103908, 2024). "To assess the combined treatment efficacy of ESYT3 overexpression and radiotherapy, we constructed xenograft tumor models." (PMID 39103908, 2024). "Overexpression of ESYT3 in the combination of irradiation displayed a good effect in hindering in vivo tumor growth." (PMID 39103908, 2024). "Especially, we discovered ESYT3 as a tumor suppressor and a novel radioimmune response sensitizer for LUAD, which can activate cGAS-STING-dependent DNA damage response through directly interacting with STING, acting as a potential treatment target for improving LUAD prognosis." (PMID 39103908, 2024). "We discovered ESYT3 as a tumor suppressor as well as a novel radioimmune response sensitizer." (PMID 39103908, 2024).
cancer (1 paper, 2024). A tumor composed of atypical neoplastic, often pleomorphic cells that invade other tissues. "More importantly, the combination treatment of ESYT3 overexpression with radiotherapy exerted a synergistic anti-cancer effect, providing a possible combination treatment strategy against LUAD." (PMID 39103908, 2024).
ESYT3 also shares sentences with these, for which no sentence is quoted: metabolic syndrome (1 paper); Obesity (1).